NOS1AP (nitric oxide synthase 1 adaptor protein)
Diseases named in the same sentence as NOS1AP in open-access papers (continued):
Sharing a sentence is not in itself a finding about the gene and the disease.
breast carcinoma (7 papers, 2016 to 2024). "The mRNA expression of PCP-related genes VANGL2, NOS1AP, SCRIB, WNT11 and SMURF2 in VANGL2- or NOS1AP-amplified breast cancers (most cases are co-amplified) is heterogeneous in molecular sub-types." (PMID 36675340, 2023). "VANGL2 and NOS1AP are located at neighboring loci 1q23.2 and 1q23.3 and are amplified in 8.8% and 9.1% of breast cancer cases of TCGA cohort, respectively." (PMID 36675340, 2023). "NOS1AP mRNA is not consistently over-expressed in any of the four sub-types in VANGL2- or NOS1AP-amplified breast cancers." (PMID 36675340, 2023). "In contrast, luminal B and HER2-dependent VANGL2/NOS1AP-amplified breast cancers show over-expression of VANGL2 mRNA only occasionally." (PMID 36675340, 2023). "The expression of NOS1AP is moderate in about half of the breast cancer cases with two of the three antibodies used (HPA030066 and HPA055561) and low to absent when a third antibody (CAB018582) was used." (PMID 36675340, 2023). "Interestingly, SCRIBBLE and SMURF2 mRNAs are also over-expressed in several cases of basal VANGL2- or NOS1AP-amplified breast cancers but rarely in other subtypes." (PMID 36675340, 2023). "In addition, VANGL proteins serve as the docking site for SCRIB and NOS1AP, and the VANGL/SCRIB/NOS1AP complex promotes cell migration in breast cancer cells." (PMID 36675340, 2023). "However, CRISPR and RNAi knockdown revealed no recurrent dependencies characterizing these cell lines with SCRIB, VANGL2 and NOS1AP amplifications that could suggest therapeutic avenues in breast cancers with these amplifications." (PMID 36675340, 2023). "Despite the association of the different NOS1AP isoforms with distinct localized YAP pools, both NOS1APa and NOS1APc are capable of reducing cellular proliferation, consistent with previous work showing that NOS1APa functions as a tumor suppressor in breast cancer models." (PMID 28222762, 2017). "In light of this complex molecular choreography, and its important role for breast cancer, it will be important to biochemically and structurally determine the binding characteristics of SCRIB, NOS1AP and KANK1 in future." (PMID 39613731, 2024). "Two of the four breast cancer cell lines with SCRIB, VANGL2 and NOS1AP concomitant amplification in the CCLE collection display sensitivity to porcupine inhibitors, and one of them also shows sensitivity to drugs affecting the PI3K/AKT/mTOR pathway." (PMID 36675340, 2023). "In an exploration of cell line models, two of the four breast cancer cell line models with amplifications in VANGL2, NOS1AP and SCRIB display sensitivity to drugs inhibiting acyl-transferase porcupine interfering with the WNT pathway." (PMID 36675340, 2023). "Thus, the VANGL/SCRIBBLE/NOS1AP PCP complex may be involved in breast cancer metastasis." (PMID 36675340, 2023). "VANGL2 mRNA is over-expressed in many luminal A VANGL2/NOS1AP-amplified breast cancers and in most basal VANGL2- or NOS1AP-amplified breast cancers." (PMID 36675340, 2023). "The current study examines the role of core components of PCP in breast cancer and focuses on members of the VANGL/SCRIBBLE/NOS1AP complex, which display copy number alterations in a sizable minority of mammary carcinomas." (PMID 36675340, 2023). "In breast cancer, VANGL1 co-localizes with SCRIBBLE and NOS1AP (Nitric Oxide Synthase 1 Adaptor Protein) in cellular protrusions and regulates the migration of cells." (PMID 36675340, 2023). "Breast cancer cell lines with NOS1AP locus amplifications (feature cnaBRCA64 in GDSC) show no differential sensitivity to either porcupine or tankyrase inhibitors compared with breast cancer cell lines without the amplification feature cnaBRCA64." (PMID 36675340, 2023). "The dependency evaluation of the cell lines with SCRIB, VANGL2 and NOS1AP amplifications with CRISPR and RNAi revealed several genes involved in breast cancer pathogenesis, such as FOXA1, ERBB2, PIK3CA and CDK4, to be among the top preferential essential genes." (PMID 36675340, 2023).
breast carcinoma (continued). "Whether and how NOS1AP influences breast cancer in vivo is not known." (PMID 39613731, 2024). "mRNA expression of VANGL2, NOS1AP and SCRIB is not prognostic of survival in breast cancer as a whole or in the subsets of luminal A, luminal B, HER2 and basal cancers (Log Rank p corrected for multiple comparisons >0.05; not shown)." (PMID 36675340, 2023).
diabetes (7 papers, 2008 to 2024). "There are a number of articles indicating a contribution of NOS1AP variants to prolongation of the QT interval in patients with diabetes mellitus, which is a risk factor for cardiovascular events." (PMID 38540239, 2024). "The relationship between different variants of the NOS1AP gene and the incidence of diabetes mellitus has been documented." (PMID 38540239, 2024). "This study was designed to investigate a potential association of PPARD rs2016520 (T/C) and NOS1AP rs12742393 (A/C) polymorphisms with efficacy of nateglinide in newly diagnosed Chinese patients with type 2 diabetes mellitus (T2DM)." (PMID 34772419, 2021). "In Chinese individuals, 20 SNPs of NOS1AP are reported to be nominally associated with type 2 diabetes mellitus; according to a meta-analysis, there is a statistically significant association between rs12742393 and type 2 diabetes mellitus (OR 1.17, 95% CI 1.07–1.26)." (PMID 38540239, 2024). "A number of articles have been published indicating the participation of NOS1AP in the development of diabetes mellitus." (PMID 38540239, 2024). "Several specific genes in this region, such as LMNA, NOS1AP and ATF6, were identified that they might confer risk for diabetes in some populations." (PMID 21211013, 2011). "Additionally, the PKLR and the NOS1AP genotypes were demonstrated not to have a major influence on diabetes-related quantitative metabolic phenotypes." (PMID 19111066, 2008).
Obesity (5 papers, 2008 to 2024). Accumulation of substantial excess body fat. "We failed to provide evidence of an association between PKLR rs3020781 and NOS1AP rs7538490 and type 2 diabetes, overweight, obesity or related quantitative metabolic phenotypes in large-scale studies of Danes." (PMID 19111066, 2008).
Arrhythmia (4 papers, 2017 to 2023). Any cardiac rhythm other than the normal sinus rhythm. "So far, an increase in L-type calcium current (which is also enhanced by sympathetic activation) due to CAPON under expression has been advocated as the main mechanism responsible for NOS1AP genetic variant impact on QT interval duration and arrhythmias susceptibility." (PMID 30972341, 2019). "Given that the over‐expression of Nos1ap per se has a detrimental effect on CaV1.2 conductance, our study suggests that targeting of the protein expression of Nos1ap could be a relevant future strategy for prevention of cardiac arrhythmia." (PMID 36352324, 2023). "No rhythm disorders were recorded in non‐induced mice (P < 0.01 for arrhythmias vs. no arrhythmias in non‐induced or Nos1ap over‐expressing mice)." (PMID 36352324, 2023).
long QT syndrome (4 papers, 2007 to 2023). "Among 88 SNPs (MAF ≥ 0.10, call rate ≥ 0.8, HWE p-value ≥ 0.001) in 9 genes implicated in congenital Long QT Syndromes or QT interval duration, only SNPs in NOS1AP had p < 0.05 for association with QT interval duration." (PMID 17903306, 2007). "This study first demonstrates that a genetic polymorphism in NOS1AP may attenuate methadone-associated QTc prolongation, which might confer a protective effect to some extent, of drug-induced long QT syndrome and sudden cardiac death in men with heroin dependence taking methadone." (PMID 35629257, 2022).
type 2 diabetes (4 papers, 2008 to 2024). "Our previous study showed evidence that rs12742393 in NOS1AP was involved in type 2 diabetes susceptibility in the Chinese population, with C allele as the risk allele (OR 1.17, 95% CI 1.07–1.26; P = 0.0005)." (PMID 23671866, 2013). "We have previously identified a novel variant rs12742393 of NOS1AP for type 2 diabetes susceptibility in the Chinese population." (PMID 23671866, 2013). "In addition, genetic studies have implied that the variations in NOS1AP are associated with reduced glucose lowering effect in sulfonylurea users as well as increased incidence of type 2 diabetes in patients taking calcium channel blockers." (PMID 23671866, 2013). "The C-allele of PKLR rs3020781 and the T-allele of NOS1AP rs7538490 are reported to strongly associate with type 2 diabetes in various European-descent populations comprising a total of 2,198 individuals with a combined odds ratio (OR) of 1.33 [1.16–1.54] and 1.53 [1.28–1.81], respectively." (PMID 19111066, 2008). "Therefore, apoA4, the only upregulated protein in the risk allele carriers in our research, might have an association with type 2 diabetes through the interaction with NOS1AP (or nNOS)." (PMID 23671866, 2013).
Hypertension (3 papers, 2018 to 2024). The presence of chronic increased pressure in the systemic arterial system. "The gene with the most plausible functional link to BP regulation or hypertension risk in this study is the NOS1AP (nitric oxide synthase 1 (neuronal) adaptor protein) gene." (PMID 29343252, 2018). "Interestingly, several genes in the chromosome 1q linkage region, in which NOS1AP falls, have previously been reported to be associated with hypertension which motivates for this gene and regions on chromosome 1 to be investigated further for their role in BP/hypertension." (PMID 29343252, 2018). "Additionally, β-adrenergic receptor (ADRB2) and nitric oxide synthase-1-adaptor protein (NOS1AP) are part of the sympathetic and para-sympathetic nervous systems and are known to be involved in the pathophysiology of hypertension." (PMID 36011305, 2022).
mental disorder (3 papers, 2020 to 2022). A disease that has its basis in the disruption of mental process. "In our review, we have summarized information regarding all NOS1, NOS2, NOS3, and NOS1AP single nucleotide variants (SNVs) involved in the development of mental disorders and neurological diseases/conditions." (PMID 32111088, 2020). "NOS1AP and its interaction with nNOS have been associated with several mental disorders." (PMID 34455393, 2021). "Overexpression of NOS1AP in the hippocampus promotes the development of endophenotypes related to mental disorders." (PMID 36012368, 2022). "Increased expression and protein overproduction of NOS1AP have been shown in the brain samples of patients with mental disorders, especially SCZ." (PMID 36012368, 2022). "Strong support for a functional role of NOS1AP to various mental disorder (endo)phenotypes was provided by the COGS family study." (PMID 34455393, 2021). "Taken together, we demonstrate a potential importance of hippocampal NOS1AP in the pathophysiology of different mental disorders." (PMID 34455393, 2021). "In our review, we have decided to summarize information regarding all NOS1, NOS2, NOS3, and NOS1AP SNVs involved in the development of mental disorders and neurological diseases/conditions." (PMID 32111088, 2020). "Nitric oxide synthase 1 adaptor protein (NOS1AP; previously named CAPON [Carboxy-terminal PDZ ligand of neuronal nitric oxide synthase]) is a scaffolding protein that has been linked to different mental disorders." (PMID 34455393, 2021). "Increased hippocampal NOS1AP might thus give rise to a specifically altered behaviour that contributes to mental disorders in a transdiagnostic manner, pinpointing the network-specific molecular underpinnings of these cross-disorder symptoms." (PMID 34455393, 2021). "Thus, this study enabled us to distinctly identify the contribution of hippocampal NOS1AP to phenotypes related to mental disorders." (PMID 34455393, 2021). "Despite the high levels of NOS1AP expression in the hippocampus and the relevance of this brain region in glutamatergic signalling as well as mental disorders, a potential role of hippocampal NOS1AP in the pathophysiology of these disorders has not been investigated yet." (PMID 34455393, 2021).
ventricular fibrillation (3 papers, 2008 to 2023). A disorder characterized by an electrocardiographic finding of a rapid grossly irregular ventricular rhythm with marked variability in QRS cycle length, morphology, and amplitude. "Recently, genome-wide association studies have found a common variant in the nitric oxide synthase 1 adaptor protein (NOS1AP) to be associated with QT-interval variation but increased risk for ventricular fibrillation and sudden death could not yet be established." (PMID 19440513, 2008).
autism (2 papers, 2018 to 2021). Persistent deficits in social interaction and communication and interaction as well as a markedly restricted repertoire of activity and interest as well as repetitive patterns of behavior. "Four genes cg23920016 (NOS1AP), cg24274662 (MOSPD1), cg26017408 (AFAP1L2) and cg16930349 (GRIPAP1) identified based on predictive ability for autism using AI analysis." (PMID 34260616, 2021).
brain arteriovenous malformation (2 papers, 2017 to 2021). "Our previous study proved that regular tobacco smoking could increase the methylation of nitric oxide synthase 1 adaptor protein, and could increase the risk of IA and cerebral arteriovenous malformations in Han Chinese." (PMID 34295240, 2021).
sudden cardiac arrest (2 papers, 2011 to 2017). Unexpected rapid natural death due to cardiovascular collapse within one hour of initial symptoms. "We also assessed 4 recently published gene associations for sudden cardiac arrest, validating NOS1AP (p = 4.50 × 10-2, OR = 1.15, 95% CI:1.003, 1.326), CSMD2 (p = 6.6 × 10-3, OR = 2.27, 95% CI:1.681, 2.859), and AGTR1 (p = 3.00 × 10-3, OR = 1.13, 95% CI:1.042, 1.215)." (PMID 21658281, 2011).
ventricular tachycardia (2 papers, 2017 to 2023). A disorder characterized by an electrocardiographic finding of three or more consecutive complexes of ventricular origin with a rate greater than a certain threshold (100 or 120 beats per minute are commonly used). "We here found a decrease of APD90 paralleled by a decrease of the QT interval and spontaneous ventricular tachycardias with a decreased survival rate (60% after 3 months) in the Nos1ap over‐expressing mice." (PMID 36352324, 2023). "Nos1ap over‐expression resulted in a shortening of the QT interval on ECG, ventricular tachycardias and decreased survival rate without evidence of structural cardiac diseases." (PMID 36352324, 2023).
heart failure (1 paper, 2023). Inability of the heart to pump blood at an adequate rate to meet tissue metabolic requirements. "LV diameter, NT‐proBNP as a surrogate marker for heart failure and extent of myocardial fibrosis were similar in Nos1ap over‐expressing mice and controls." (PMID 36352324, 2023). "In addition, quantitative NT‐proBNP measurements gave no signs of heart failure due to induction of the transgenic phenotype (1.16 ± 0.8 in non‐induced to 1.25 ± 0.85 in Nos1ap over‐expressing mice, P > 0.05)." (PMID 36352324, 2023).
heroin dependence (1 paper, 2022). Physical and psychological dependence on the drug heroin. "We investigated whether common NOS1AP variants interact with methadone in relation to QTc prolongation in patients with heroin dependence." (PMID 35629257, 2022). "We thus conducted a prospective cohort study to assess whether common NOS1AP variants interact with methadone in relation to QTc prolongation in patients with heroin dependence." (PMID 35629257, 2022).
idiopathic ventricular tachycardia (1 paper, 2017). "In this study, we test the association between the variation rs12143842 in NOS1AP and idiopathic ventricular tachycardia (IVT)." (PMID 28827735, 2017).
Insulin resistance (1 paper, 2021). Increased resistance towards insulin, that is, diminished effectiveness of insulin in reducing blood glucose levels. "PPARD and NOS1AP are directly or indirectly involved in the regulation of β-cell function and insulin resistance, which suggests that genetic polymorphisms in the two genes may contribute to interindividual differences in nateglinide response." (PMID 34772419, 2021).
neuroblastoma (1 paper, 2025). Neuroblastoma (NB) is the most common solid, extracranial childhood tumor. "We also analyzed the change in NOS1AP gene expression and NOS1AP protein production in SH-SY5Y neuroblastoma cells and HEK293T after MK-801 treatment." (PMID 40508138, 2025).
synucleinopathies (1 paper, 2022). "Thus, it is possible to assume that NOS1AP is implicated in the development of synucleinopathies." (PMID 36012368, 2022). "The increase of local concentration of α-synuclein in NOS1AP aggregates may promote its aggregation and development of synucleinopathies." (PMID 36012368, 2022).
Ventricular arrhythmia (1 paper, 2023). "(b) Nos1ap over‐expressing mice had a strong susceptibility to ventricular arrhythmias and decreased survival rates." (PMID 36352324, 2023). "Our study showed that myocardial over‐expression of Nos1ap leads to the shortening of the QT interval and reduces the survival rate of transgenic animals, perhaps via the development of ventricular arrhythmias." (PMID 36352324, 2023).
viral infections (1 paper, 2021). "Four additional positional candidate genes, carbonic anhydrase 10 (CA10), CWC22 spliceosome-associated protein (CWC22), DISC1 scaffold protein (DISC1), and nitric oxide synthase 1 adaptor protein (NOS1AP), have roles in pulmonary dysfunction, viral infections, or both." (PMID 34409086, 2021).
psychiatric disorder (10 papers, 2005 to 2025). A disorder characterized by behavioral and/or psychological abnormalities, often accompanied by physical symptoms. "The NOS1AP gene is also associated with several psychiatric disorders, such as attention-deficit/hyperactivity disorder (ADHD)." (PMID 40401629, 2025). "In order to test if frequent polymorphisms within NOS1AP were associated with susceptibility to psychiatric disorders, we assessed the frequency of 11 SNPs in patients and controls." (PMID 20602773, 2010). "Further genetic and functional studies are warranted to understand the role of NOS1AP in the susceptibility to psychiatric disorders." (PMID 20602773, 2010). "Nevertheless, we report the first non-synonymous variations within the human NOS1AP gene that warrant further genetic and functional investigations to ascertain their roles in the susceptibility to psychiatric disorders." (PMID 20602773, 2010). "The NOS1AP gene is associated with neurological and psychiatric diseases." (PMID 36012368, 2022). "The NOS1AP protein is associated with psychiatric disorders, mainly SCZ." (PMID 36012368, 2022). "Genetic variants of the NOS1AP gene are associated with ASD and other psychiatric diseases." (PMID 34260616, 2021). "Together, these findings make NOS1AP as a compelling candidate for several psychiatric disorders." (PMID 20602773, 2010). "Thus, NOS1AP represents an attractive novel target for psychiatric disorders." (PMID 34455393, 2021).